CD44 (CD44 molecule (IN blood group))
Diseases named in the same sentence as CD44 in open-access papers (continued):
Sharing a sentence is not in itself a finding about the gene and the disease.
cancer (continued). "In addition, simultaneous expression of all three analysed putative cancer stem cell markers (CD44, CD133 and CD166) was found in 0.5–53.6% of cells (median 2.0%)." (PMID 41303421, 2025). "Indeed, CD44 is considered a cancer stem cell marker where immunohistochemical analysis of human HCC samples demonstrate increased expression of CD44." (PMID 40034259, 2025). "Therefore, in this study, for the first time, we investigated the relative expression and co-expression and prognostic significance of all members of the HER family with EGFRvIII, and cancer stem cell biomarkers CD44 and CD109 in patients with GBM." (PMID 40227788, 2025). "Therefore, HA, a desirable target ligand for CD44, is widely used as an active targeted drug delivery system to enhance anticancer drug delivery to CD44-overexpressing cancer cells." (PMID 39997114, 2025). "This study examined whether the expression of EGFRvIII is accompanied by the co-expression with other members of the HER family and putative cancer stem cell biomarkers CD44 and CD109." (PMID 40227788, 2025). "Specifically, expression changes in SNAI1, CD44 and ALDH1A3 genes were positively associated with the viable cancer cell fraction (rs > 0.5 and p < 0.05), suggesting that PDS cultures promoting CSC features might be less susceptible to T cells action." (PMID 40240529, 2025). "This enhanced interaction profile suggests that HA-functionalized DDS2 may achieve superior targeting to CD44-overexpressing cancer cells, improving drug delivery efficacy." (PMID 40573202, 2025). "However, when these cells were treated with varying concentrations of LA (10, 25, and 50 μM), the proportion of CD44+ cancer stem cells decreased significantly, dropping from 21.5% to 7.3% as observed in flow cytometry analysis." (PMID 40864800, 2025). "Our analysis of HCC using the TCGA database confirmed the correlation of TKT with additional ICP genes, including CD44, CD80, CD86, and CTLA-4, which may explain the association of TKT overexpression with poorer prognoses in patients with cancer." (PMID 40230848, 2025). "Around half (55%) of tumors had cancer cells that were double positive for CD44 and CD24." (PMID 40943144, 2025). "Gene ontology by overrepresentation analysis revealed that CD44 KO iMG significantly upregulated genes related to DNA replication and cell cycle checkpoint signaling, consistent with the role of CD44 isoforms in numerous cancer types." (PMID 41282250, 2025). "CD44 is a primary cell surface receptor for HA and a well-established cancer biomarker." (PMID 41461315, 2025). "Mechanistically, we identified that TIP60 controls cancer stemness via CD44." (PMID 40422189, 2025). "Notably, miR-34a directly targets CD44, a cell surface glycoprotein involved in tumorigenesis and metastasis, making it a compelling candidate for cancer therapy." (PMID 40869286, 2025). "The purpose was to allow the CD44 antibody–magnetic bead complex (CD44 beads), which specifically binds to the abundantly present CD44 receptors on identifiable cancer cells, to flow into the reservoir well, while the biological mixture containing the cancer cells is retained in the capture well." (PMID 40821671, 2025). "The interaction between HA and CD44 is an instrumental event in regulating inflammation and cancer." (PMID 40860188, 2025). "Overall, the strong and stable binding between SPP1 and CD44 suggests that future therapeutic strategies could involve small molecules designed to block their interaction, potentially enhancing the efficacy of cancer immunotherapy." (PMID 41425595, 2025). "CD44 is a hyaluronan receptor that is highly expressed in many cancer cells." (PMID 41259528, 2025).
cancer (continued). "Additionally, coating the nanoparticles with hyaluronic acid (HA) facilitated the specific targeting of CD-44-overexpressing cancer cells, improving delivery efficiency to the tumor site." (PMID 39852748, 2025). "Importantly, HA is a well-known specific ligand for the cluster-determinant 44 receptor (CD44), which is considered an early indicator of cancer proliferation and a cancer biomarker." (PMID 39997114, 2025). "The proportion of CD44+ cancer stem cells decreased significantly, dropping from 35.4% to 16.7%." (PMID 40864800, 2025). "CD44 is overexpressed in many cancer cells and cancer stem cells." (PMID 40001633, 2025). "The most frequently investigated mechanisms included the dysregulation of the PI3K/AKT/mTOR and MAPK signaling pathways, enhanced DNA damage repair via non-homologous end joining (NHEJ), and the overexpression of cancer stem cell markers such as CD44+/CD24−/low and ALDH1." (PMID 40864743, 2025). "Dysregulation in CD44–MMP and CD44–fibronectin pathways contributes to pathological conditions, highlighting their potential as therapeutic targets for restoring physiological balance in cancer." (PMID 40363706, 2025). "MiR-204 inhibits CD44 (cancer stem cell marker) in HCC827/gef and H1975/AZD18 NSCLC cells (resistant cells to osimertinib by continuous exposure to this TKI), repressing the pluripotency of these cells by reducing spheroid formation and promoting osimertinib-induced apoptosis." (PMID 40283927, 2025). "Upregulation of other cancer-associated genes in MPOSE – such as Ccnd1, Btc, Ankrd1, Oraov1, Cd44 and Ifitm3 – as well as possible DNA mutations or fusions, may also contribute to tumorigenic differences and warrant further investigation." (PMID 40642792, 2025). "More recent reviews discuss the role of its tissue-expressed form in cancer, including nanobiosensing approaches for early cancer detection in CD44-expressing cells, a particular form of cancer, or the intracellular domain of CD44." (PMID 41440277, 2025). "The use of multiple conjugates against antigens expressed on differentiated PC cells and PCSC cells, e.g., CD44 and EpCAM, could be an effective method to eradicate the heterogeneous population of residual cancer cells completely." (PMID 39846613, 2025). "The prepared HA-CQD surface actively targets CD44-positive cancer cells." (PMID 40363642, 2025). "Many studies have reported that high expression CD44 predicts poor prognosis in other cancer types." (PMID 40227788, 2025). "miRNAs such as hsa-mir-196a-5p and hsa-mir-29a-5p regulate the expression of cell adhesion molecules, including CD44, ICAM1, and ITGA3, and may therefore be associated with cell migration and cancer metastasis." (PMID 41226241, 2025). "Although CD44 expression is recognized as a definite independent prognostic factor in various cancers, CD44 isoforms have increasingly attracted attention due to their much more specific expression in cancer stem cells and their various functions via signalling transduction compared with CD44." (PMID 40227788, 2025). "Moreover, CD44 is typically overexpressed in cancer cells, which underscores the relevance of ERM proteins in the cell adhesion to substrates." (PMID 40141408, 2025). "HA has been employed for cancer therapy using its immunostimulatory and CD44‐targeting properties." (PMID 41287898, 2025). "In colorectal cancer, GA activated the miR-199a-3p-mediated inhibition of the Wnt/β-catenin pathway, promoting efficient β-catenin ubiquitination and degradation, thereby effectively suppressing the self-renewal capacity of the CD133+/CD44+ cancer stem cell subpopulation." (PMID 41311720, 2025). "For roles in cancer, most solid malignancies contain cancer stem cells characterized by CD44." (PMID 40558504, 2025). "Total CD44 is additionally known to regulate autophagy in cancer cells." (PMID 40114966, 2025).
cancer (continued). "Cancer stem cells (CSCs) are a therapy-resistant subgroup with renewal capacity and mesenchymal features and often identified positive for Cluster of Differentiation-44 (CD44)." (PMID 40430044, 2025). "In vitro studies regarding the beneficial effects of cinnamic acid on cancer stem cells revealed it positive effect on HT-29 colorectal CSC (CD44+, CD133+ populations) with decreased viability and the down-regulation of stemness markers (Oct4, Nanog, ALDH1, ABCB1)." (PMID 39859345, 2025). "Here, by coupling aptamer-based affinity purification and subsequent mass spectrometry (MS)-based proteomics with a systematic approach that takes advantage of the different binding affinity of sTN58 to different cancer cell lines, we succeeded in identifying CD44 as the target of sTN58." (PMID 40342488, 2025). "CD44 plays a major role in regulating cancer cell proliferation and metastasis." (PMID 39996744, 2025). "As we know, CD44 promotes the progression of cancer by activating crucial signaling pathways." (PMID 40607003, 2025). "Conceivably, a caveat when attempting passive or active cancer eradication through CD44 may turn out to be its widespread distribution in healthy tissue of the body." (PMID 39980017, 2025). "CD44 is involved in drug resistance mechanisms, namely in cancer stem cells." (PMID 41367861, 2025). "Therefore, we will improve its ability to capture cancer cells by optimizing the strength of the magnetic field and adjusting the CD44 micro-bead concentrations." (PMID 40821671, 2025). "Utilizing multiple conjugates against antigens expressed on differentiated PC and PCSC-like cells, such as CD44 and EpCAM, could be an effective method to eradicate residual cancer cells in heterogeneous tumors." (PMID 39846613, 2025). "This study demonstrates that carvacrol exerts multi-targeted anticancer effects in both HR+ (MCF-7) and TNBC (MDA-MB-231) BC cells by enhancing the BAX/BCL2 ratio, inducing apoptosis, reducing oxidative stress, and downregulating CD44+ cancer stem cell marker levels." (PMID 41154846, 2025). "Moreover, post-translational modifications of CD44, such as glycosylation, frequently become deregulated in cancer." (PMID 40507943, 2025). "CD44, as a marker of cancer stemness and EMT, and xCT, related to redox metabolism and chemoresistance, identify high-risk SCC subpopulations that may require more aggressive treatment strategies." (PMID 40427131, 2025). "The first one was employed by Wang and colleagues, who developed hyaluronic acid-block-poly(D,L-lactide-co-glycolide) (HA-b-PLGA) micelles encapsulating PPIX to create a drug delivery system of improved PDT specificity and effectiveness targeting CD44-overexpressing cancer cells." (PMID 41374877, 2025). "CD44 isoforms play distinct functional roles in cancer biology." (PMID 40759634, 2025). "Similarly, CD44 has been identified as a cancer stemness marker involved in immunomodulation, particularly in bone marrow-derived MSCs." (PMID 40646808, 2025). "However, despite the mounting evidence supporting CD44-targeted strategies in various cancers, research on this therapeutic potential in TC remains limited." (PMID 40363706, 2025). "CD44 is highly expressed in cancer cells and serves as a key marker for cancer stem cells (CSCs)." (PMID 40507943, 2025). "The functions of CD44 involved in regulation of cancer signaling pathways are being actively studied, and the significance of specific variant exons in modulating cell death pathways, central to the response of cancer cells to chemotherapy, begins to become apparent." (PMID 40114966, 2025). "CD44 has been identified as a marker for cancer stem cells and a key factor in cancer development." (PMID 40046628, 2025). "The expression of CD44 may identify a population of cancer stem cells with potential involvement in metastatic spread, which is further supported by high protein levels of c-Myc in this cell population." (PMID 40395327, 2025).
cancer (continued). "These proteins, including ICAM-1, SPPL2A, CD276, and CD44, may help the cancer cells stick together, spread, and avoid the immune system." (PMID 40805206, 2025). "Since specific isoforms of CD44 may play a more critical role in certain cancers, their quantitative detection is crucial." (PMID 41440277, 2025). "The role of CD44 in cancer is complex and often appears contradictory." (PMID 41514534, 2025). "Ligand receptor analysis revealed that APOE+ macrophages may interact with cancer cells via the SPP1‐CD44 and FN1‐SDC4/CD44 signaling pathways, whereas monocytes and DCs may interact with cancer cells via the LGALS9‐CD44 signaling pathway." (PMID 40492378, 2025). "In addition, curcumin down-regulates the expression of cancer stem cell markers (CD44 in MDA-MDB-231 cell line) and Hedgehog signaling pathways (in SUM159 and MCF7 cell lines)." (PMID 39859345, 2025). "Given that the plasticity of CD44 isoforms plays a crucial role in cancer stem cell adaptation, ZMAT3-mediated regulation of CD44 splicing may shift this balance, ultimately suppressing CSC properties." (PMID 40259468, 2025). "Furthermore, CD44‐HA binding has a roll‐on effect that enhances the treatment resistance properties of cancer cells via increased multidrug resistance protein 1 (MDR1) expression and epithelial‐to‐mesenchymal transition (EMT) pathway upregulation." (PMID 40888184, 2025). "By leveraging these advancements, this work demonstrates a streamlined, high-throughput platform for selecting X-aptamers with optimized chemical diversity and enhanced functional performance against CD44, offering potential applications in targeted cancer diagnostics and therapeutics." (PMID 40001633, 2025). "Moreover, presumptive dormant cells acquired cancer stem cell–like characteristics, including upregulation of CD44 and ALDH1." (PMID 41365861, 2025). "Moreover, CD44+ malignant cells are widely recognized as crucial factors in maintaining cancer stemness and immune suppression." (PMID 40406147, 2025). "HA, a negatively charged linear polysaccharide, was integrated into the formulation to enhance colloidal stability of PCNs and provide active tumor-targeting capabilities through specific binding to CD44, a receptor overexpressed in many cancer types, including colon cancer." (PMID 40869286, 2025). "Therefore, this review comprehensively discusses the role of soluble CD44 as a marker in various cancer types, including serum, saliva, urine, and other fluids." (PMID 41440277, 2025). "The CD44 protein increases its expression on the cancer cell’s surface." (PMID 40670469, 2025). "Thus, many investigations have analysed HA-coated nanocarriers for targeting CD44 over-expressing cancer cells." (PMID 40264886, 2025). "It is well accepted that CD44 is crucial in regulating cancer metastasis." (PMID 40409554, 2025). "There are two isoforms for CD44, standard (CD44s) and variant (CD44v), with CD44v being involved in metastasis, epithelial-to-mesenchymal transition (EMT), and the adaptive plasticity of cancer cells." (PMID 40005368, 2025). "Finally, we focused on ROK signaling, which is activated by the interaction of HMW-HA with CD44 in various cells, including keratinocytes, osteoblasts, and cancer cells." (PMID 40002789, 2025). "In addition, CD318 and CD44 are compelling markers for cancer stem cells of many solid malignancies such as breast cancer and prostate cancer." (PMID 39996744, 2025). "This seemingly contradictory result suggests that CD44 may have dual roles depending on the cellular context and the specific cancer type." (PMID 39833941, 2025). "Additionally, the tumorigenicity of breast and other cancer types can be influenced by changes in the expression of miRNAs that regulate CD44 expression." (PMID 40587726, 2025).
cancer (continued). "Further, gene expression of cancer cells showed upregulation of stemness associated genes NANOG, OCT4, CK14 and CD44 in two different cancer cell lines exposed to CM of TGF-CAF compared to that of UT-CAF; suggesting the possibility of induction of stemness in cancer cells by TGF-CAF." (PMID 40349056, 2025). "The analysis displayed in the GEO database indicated that the expressions of the Warburg effect key enzyme PKM2, CSC reprogramming factors OCT4 and KLF4 and cancer stemness marker CD44 in HBV(+) HCC were higher than those of HBV(−) HCC, with statistical significance, p < 0.05." (PMID 40717222, 2025). "This suggests that targeting CD44 could be an effective strategy to overcome drug resistance in cancer patients with P-gp overexpression." (PMID 40534867, 2025). "Previous studies have reported that CD44 interacts with TGFβR1 30 or EGFR 29 in cancer." (PMID 40860188, 2025). "CD44-targeted nanocarriers have garnered attention for their potential in cancer therapy." (PMID 41367861, 2025). "CD44, a hyaluronic acid receptor, is a cancer stem cell marker and activates STAT3." (PMID 40683954, 2025). "Given that leader cells frequently exhibit to be more motile and invasive than followers, it is reasonable to speculate that CD44 enrichment in leader cells may be indispensable for cancer cell collective migration." (PMID 40409554, 2025). "Further studies are necessary to clarify the exact relationship between CD44 variant expression and ATC’s clinical outcomes, which could enhance targeted therapeutic strategies for this challenging cancer." (PMID 40363706, 2025). "Additionally, prior research has noted that the BCSC marker CD44 is a standard marker of CTCs of various cancers." (PMID 40869256, 2025). "In the Hippo pathway, CD44 plays key role in cancer stemness and aggressive behavior." (PMID 38783892, 2024). "Researchers have successfully used HA to target CD44-overexpressing cancer cells." (PMID 38672650, 2024). "Additionally, the combination therapy substantially downregulated the expression of the stemness gene Sox2 and the cancer stem cell marker CD44, contrasting with the effects of single MRTX1133 treatment." (PMID 39297408, 2024). "HA produced by stromal cells and cancer cells is a major ligand for CD44." (PMID 38791985, 2024). "Our laboratory identified CXCR4-, MET- and CD44-enriched cancer stem cells (CSCs) in human ccRCCs." (PMID 38512983, 2024). "Our finding that the expression levels of KRT-14, SOX2, CD44, and ALDH1a decreased upon si-m/hVDAC1-B BC treatment suggests that the metabolic reprogramming of cancer cells via VDAC1 depletion reduces CSC markers, suggesting the inhibition of their proliferation and/or induction of differentiation." (PMID 38607066, 2024). "Subsequent in vitro and in vivo studies confirmed NP accumulation in cancer cells, attributed to the CD44-targeting property of HA, thus enhancing NP uptake into cancer cells, low cytotoxicity, minimal accumulation in other organs, and up to 44% reduction in SET1 expression post-cancer cell lysis." (PMID 39065565, 2024). "Moreover, it should be mentioned that CD44 is also involved in the regulation of cell adhesion and migration, and it is an important regulator of cancer cell progression and metastasis." (PMID 39004641, 2024). "The HA receptor CD44 is upregulated in cancers of numerous origins." (PMID 39726703, 2024). "Antibody against CD44 has been reported to be used in this way in CD44‐positive cancer." (PMID 38783892, 2024). "In addition to RPE, CD44 is highly expressed in many cancers and has a crucial role in regulating metastasis via recruitment of CD44 to the cell surface of the cancer cells." (PMID 39840036, 2024).